BDNF (brain derived neurotrophic factor)
Diseases named in the same sentence as BDNF in open-access papers (continued):
Sharing a sentence is not in itself a finding about the gene and the disease.
tumor (continued). "BDNF (100 ng/ml) significantly increased the number of anoikis-resistant tumor cells (floating viable tumor cells with non-adherent growth), as compared with non-treated controls." (PMID 24801982, 2014). "Blockade of PAR2 signaling by FSLLRY-NH2 significantly reversed the upregulation of spinal BDNF in the rats implanted with tumor cells, while it did not obviously change the expression of spinal BDNF in the control rats." (PMID 24886294, 2014). "The proportion of apoptotic tumor cells (lower right quadrant+upper right quadrant) was decreased by BDNF (DLD1; 26.0%→21.9%, SW480; 18.6%→11.9%, LoVo; 25.6%→15.6%), suggesting an anti-apoptotic effect by BDNF." (PMID 24801982, 2014). "The current study demonstrates that MM-derived BDNF promotes osteoclast formation via upregulation of RANKL expression in vitro, and antisense inhibition of BDNF in ARH-77 cells blocks osteolytic bone destruction and tumor growth in SCID-rab mice." (PMID 23077504, 2012). "After exposure to BDNF for 24 hours, stimulation with BDNF resulted in increased phosphorylation of various kinases, Akt, Src, and MAPK in parental cells, consistent with previous studies regarding its role in tumor proliferation and apoptosis." (PMID 22276165, 2012). "In addition to their effects on immune cells, tumor-derived neuropeptides interact with neurotrophic factors such as Nerve Growth Factor (NGF) and Brain-Derived Neurotrophic Factor (BDNF), which are critical for axonogenesis and nerve recruitment inside the TME." (PMID 40805163, 2025). "Cancer cells release neurotrophins like Nerve Growth Factor (NGF), Brain-Derived Neurotrophic Factor (BDNF), Glial Cell Line-Derived Neurotrophic Factor (GDNF), and artemin (ARTN), which bind to receptors on nerve cells, promoting neurite outgrowth toward the tumor." (PMID 40909268, 2025). "β-adrenergic antagonists diminish catecholamine-induced BDNF up-regulation and enhance CD8+ T-cell infiltration, making them logical, low-toxicity partners for neurotrophin-axis inhibitors or for anti-PD-1/PD-L1 antibodies once target engagement has curtailed tumour-intrinsic growth signals." (PMID 41142827, 2025). "Also, BDNF, GDNF, NGF, and axon guidance molecules, such as CX3CL1, EphA2, CCL2, Slit, and so forth, are groups of neuroactive chemicals generated by the nerves involved in tumor–nerve interaction." (PMID 39346791, 2024). "Interaction between GBM cells from the secretion of BDNF and the neurotrophic receptor tyrosine kinase 2 (NTRK2) expressed on GSCs has contributed to the paracrine effect, ultimately promoting malignant progression through enhanced tumour growth and development." (PMID 37686652, 2023). "Additionally, in the observational group, BDNF concentrations in tumor tissues did not correlate significantly with CSF concentrations (rho=0.36, p=0.11)." (PMID 38050515, 2023). "None of the examined factors influenced CSF, plasma, or tumor tissue BDNF concentrations (p>0.05)." (PMID 38050515, 2023). "To investigate the involvement of the BDNF/TRKB pathway in the interaction between PGC cells and the surrounding niche, we first examined the distribution and expression levels of BDNF and TRKB in the tumor tissues of patients with PGC using immunohistochemical analysis." (PMID 36266462, 2022). "That hypothesis suggested that the BDNF concentration might not depend on tumour tissue mass; rather, it might depend on the aggressiveness of a growing tumour." (PMID 34395067, 2021). "Serum BDNF levels depended on tumour aggressiveness, rather than on tumour tissue mass." (PMID 34395067, 2021). "However, to our knowledge, no study has investigated the relationship between BDNF levels in cancer tissue and tumour mass." (PMID 34395067, 2021). "In HPV− HNSCC patients, tumor cells did not die after chemotherapeutic challenge and BDNF with TGF-β1 could improve tumor cell survival and contribute to worse patient prognosis." (PMID 30641914, 2019).
tumor (continued). "Taken together, these data suggest that selective blockage of the BDNF/TRKB signaling pathway by a TRKB-specific inhibitor could selectively suppress cell proliferation, migration, and invasion of BDNFhigh/TRKBhigh PD-OSCC tumor cells." (PMID 29861866, 2018). "Also, it reduced the content of CORT, ACTH, CRH, and CA125, CA153, CEA in the blood, protected the pathological changes of the hippocampus and tumor, upregulated the expression of GR, CREB, and BDNF in the hippocampus, and significantly decreased the expression of NR2A, NR2B, and CaMKII." (PMID 30581482, 2018). "In summary, we have demonstrated that BDNF-TrkB signaling plays an important role in the interaction between cancer cells (MDA-MB-231) and endothelial cells (HUVEC) and that TrkB expression in tumor cells is correlated with a poor prognosis of patients with TNBC subype cancers." (PMID 28604807, 2017). "Protein expression levels in a tissue array of tumor slices were found to be correlated with patient prognosis and the results showed that there was significant correlation of TrkB expression, but not of BDNF." (PMID 28604807, 2017). "Concerning TrkB, the other receptor for BDNF, whereas its expression was detected in RCC patients tumors, only the truncated form TrkB-95, known to be deleted for its tyrosine kinase domain was observed in both RCC cell lines, as well as in the proteins extracted from some RCC tumor samples." (PMID 27120782, 2016). "Also, there are some limitations in our present study, such as no validation of the results in clinical tumor samples, only one cell line used, and no more inhibitors targeting BDNF/TrkB signaling pathways." (PMID 27752996, 2016). "Clear cell RCC tumor tissues from 83 patients who underwent nephrectomy were processed by immunohistochemistry in Tissue Micro Array (TMA) for pro-BDNF/BDNF (both mature and immature forms recognized by a common antibody), pro-BDNF alone, as well as p75NTR, TrkB receptor or sortilin." (PMID 27120782, 2016). "The PI3K/AKT and ERK pathways in tumor cells activated by BDNF may result in cells that are not sensitive to chemotherapeutic drugs." (PMID 24255678, 2013). "However, in vivo model, endocrine actions of other tissues-derived mouse BDNF in supporting tumor cell growth cannot be ruled out." (PMID 22911740, 2012). "Therefore, we suppose that silencing of MM-derived BDNF also attenuates RANKL expression and decreases OC activity in the BM milieu, resulting in blockage of this vicious cycle, which could promote tumor growth in MM." (PMID 23077504, 2012). "Since we demonstrated that BDNF is more expressed in preneoplastic cervical lesions of HIV-infected women compared with non-infected controls, our results may indicate that BDNF is the main responsible for the increased rate of tumor initiation and progression in women with HIV infection." (PMID 37445902, 2023). "However, a significant BDNF decrease was observed specifically in the KDM5CHigh subgroup compared to the control samples; no significant variation was observed in the KDM5CLow tumor samples that displayed expression values comparable to the healthy tissues." (PMID 36142158, 2022). "Our data support the idea that BDNF/TRKB signaling may regulate tumor progression in OSCC, especially PD-OSCC, and that high expression of these molecules may be an attractive prognostic marker for tumor aggressiveness, as well as a potential target for OSCC therapies." (PMID 29861866, 2018). "Moreover, the infiltration of tumoral lymphatics was significantly downmodulated, suggesting that the absence of a functional BDNF-TrkB axis in the tumor milieu has a negative effect on lymphovascular recruitment and on the progression to lymph node metastasis in this orthotopic model." (PMID 28966935, 2017). "MSCs secrete VEGF, BDNF, NT‐3, NT‐4, GDNF, and SDF‐1α to promote neuroprotection and angiogenesis, with no endotoxin or tumor formation." (PMID 41427019, 2025).
tumor (continued). "Macrophage-derived IL-1β induces non-neuronal cells to synthesize NGF, and tumor cells can also secrete NGF and BDNF to active their Trk receptors to stimulate nerve growth." (PMID 36900158, 2023). "Various markers such as SOX4, VEGF, BDNF, and targets of the Wnt/β-catenin signaling pathway and the Notch pathway are expressed in ACC, but not equally in all tumor patients." (PMID 36835997, 2023). "In this study, after gamma irradiation of the genetically engineered BDNF-eMSCs, we observed the abrogation of MSC proliferation without affecting cell viability and BDNF secretion, and no tumor was detected from in vivo tumorigenicity testing using nude mice." (PMID 34768827, 2021). "Tumor tissue in the tongue is not suitable for Western blotting, because TRKB and BDNF are also expressed in tongue muscle and inflammatory cells." (PMID 29861866, 2018). "However, BDNF levels through i.v. injection was increased in TNFR2 KO mice, and this injection resulted in tumor growth and SCZ-like behavior (especially negative symptoms), accompanied with increased BDNF levels." (PMID 38592583, 2024). "In RK3E cells, expression of TRKBD751N did not lead to tumor formation, even with high cell numbers and in the presence of BDNF, whereas RK3E TRKBT695I+BDNF-expressing cells formed tumors with a significant longer latency compared to RK3E TRKBwt+BDNF-expressing cells." (PMID 21379385, 2011).
neurological disorders (309 papers, 2009 to 2026). "Further, BDNF plays a crucial role in most antidepressant treatments and is further associated with neurodegenerative diseases and neurological disorders such as schizophrenia." (PMID 39648800, 2024). "BDNF has been linked to neuronal survival and neurogenesis, and its dysregulation has been observed in various neurological disorders." (PMID 38891863, 2024). "BDNF is associated with the occurrence and development of various cancers as well as several cardiovascular, neurodegenerative, and neurological diseases." (PMID 39648800, 2024). "The BDNF rs6265 polymorphism was first reported in 2003 by Egan and colleagues, who associated it with various psychiatric and neurological disorders and diseases." (PMID 37462904, 2024). "This indicates that a transient increase in the CSF KYNA concentration can potentially restore BDNF production, for which deficiency underlies numerous neurological disorders." (PMID 39682677, 2024). "Brain-derived neurotrophic factor (BDNF) is a major neurotrophin whose loss or interruption is well established to have numerous intersections with the pathogenesis of progressive neurological disorders." (PMID 37626771, 2023). "The relationship between CNS and peripherally derived BDNF has been extensively discussed in the context of a range of neurological disorders, and our results raise questions regarding the mechanisms underlying the neuroprotective effects of platelet BDNF." (PMID 36970044, 2023). "Brain-derived neurotrophic factor (BDNF) promotes neuronal differentiation and survival and is implicated in the pathogenesis of many neurological disorders." (PMID 36582820, 2023). "The role of BDNF Val66Met polymorphism in neurological diseases has been explored in several studies in the past years." (PMID 35265024, 2022). "The CREB/BDNF pathway, which regulates neuronal growth, differentiation and synapse establishment, has been implicated in several neurological disorders." (PMID 35401106, 2022). "Further studies have showed that alcohol intake causes various neurological diseases via the toxic effect of various key mediators on the brain, such as inflammation, caspase-3, and the brain-derived neurotrophic factor BDNF." (PMID 35335908, 2022). "Altered serum levels of brain-derived neurotrophic factor (BDNF) are consistently linked with neurological disorders." (PMID 35354099, 2022). "A decrease in BDNF expression is associated with neuronal atrophy or death that occurs, for example, with ageing or some neurological disorders." (PMID 36077933, 2022). "In humans, low levels of BDNF are associated with a higher risk and inferior prognosis of neurological diseases." (PMID 35155523, 2021). "Because BDNF plays a crucial role in a variety of neural functions such as synaptic plasticity, it is plausible that reduced BDNF levels in the brain cause neural dysfunctions resulting in these neurological diseases." (PMID 34977362, 2021). "Brain‐derived neurotrophic factor is a neurotrophin which exerts significant functions on development and neuroplasticity of neurons and changes in BDNF expression are implicated in various psychiatric and neurological disorders." (PMID 32790238, 2020). "Several studies have investigated the roles of BDNF in aging-associated dysfunction, especially in relation to neurological disorders." (PMID 32489703, 2020). "Recently, activation of AKT and ERK kinases as well as an increase of BDNF levels have been associated with a neuroprotective effect mediated by selective S1P5 agonists in other neurological disease." (PMID 32455907, 2020). "Impaired BDNF/TrkB signaling is associated with several neurological disorders, including neurodegenerative, neurodevelopmental, and neuropsychiatric diseases, characterized, among others, by dendritic spine alterations." (PMID 32537724, 2020). "Low BDNF level or impairment of its signaling pathway is thought to be implicated in a variety of neuropsychiatric and neurological disorders." (PMID 29540150, 2018).
neurological disorders (continued). "There are several polymorphisms in neurotrophin genes that have been studied in different neurological diseases, but only BDNF polymorphisms were evaluated in the context of severe or moderate TBI." (PMID 28524074, 2017). "Brain-derived neurotrophic factor (Bdnf) has been implicated in several neurological disorders due to its widespread function in neuronal development, plasticity, differentiation and survival." (PMID 28751857, 2017). "While aberrant expression of BDNF has been implicated in neurological disorders, the transcriptional regulation of BDNF remains to be elucidated." (PMID 28272318, 2017). "Specifically, miR-206-3p has been implicated in regulating the levels of BDNF in different animal models of neurological disorders." (PMID 28838324, 2017). "Since BDNF is associated with several nervous system disorders it would be beneficial to have cellular reporter system for studying its expression regulation." (PMID 24943717, 2014). "In contrast, microglial BDNF has gained special attention as underlying neurological diseases in adult tissue, and this is mainly due to the specific role played by microglia in the CNS." (PMID 24089642, 2013). "In conclusion, our results support the role of BDNF alterations in neurodegenerative mechanisms common to different forms of neurological disorders and underline the importance of including drug treatment in the analyses to avoid confounding effects." (PMID 24024214, 2013). "Altered expression or changes in the regulation of the BDNF gene have been implicated in a variety of human nervous system disorders." (PMID 19555478, 2009). "Alterations in BDNF function have been associated with a variety of disorders of the nervous system." (PMID 19555478, 2009). "Studies using different animal models and humans show that abnormalities related to BDNF synthesis and secretion, causing a significant decrease in its levels in the brain, are associated with many neurological disorders and central nervous system (CNS) diseases." (PMID 39682677, 2024). "The elderly phase and neurological diseases are linked to the BDNF gene’s diminished expression." (PMID 37287291, 2024). "Using the Steiger test, reverse analyses revealed that plasma BDNF levels may be causally unaffected by each specific neurological disease trait." (PMID 38707431, 2024). "In particular, the BDNF/TrkB signaling pathway plays a key role in maintaining the normal function of neuronal cells in the nervous system, and its abnormalities are directly linked to various neurodegenerative and neurological diseases." (PMID 39648800, 2024). "Dysregulation of BDNF-TrkB signaling is associated with various neurological disorders." (PMID 39595072, 2024). "Furthermore, low levels of BDNF have been associated to neurological disorders including Alzheimer’s and Parkinson’s disease." (PMID 38931243, 2024). "Low levels of BDNF are implicated in the pathophysiology of neurological diseases including AD." (PMID 35692417, 2022). "As previously stated, the expression of BDNF has been associated with neurological disorders." (PMID 35628626, 2022). "Dysregulationof BDNF signaling is implicated in different neurological disorders.The direct NT administration as therapeutics has revealed to be challenging.This has prompted the design of peptides mimicking different regionsof the BDNF structure." (PMID 36346920, 2022). "Low BDNF levels have been linked to the pathophysiology of neurological diseases such as AD." (PMID 35692417, 2022). "While the contribution of the brain-borne BDNF to the platelet pool is still unclear, circulating levels of BDNF are associated with multiple neurological diseases, suggesting that peripheral BDNF could be used as a model of neuronal BDNF levels." (PMID 33643311, 2021). "The Neurotrophin BDNF has been widely implicated in neurological disorders and in particular in AD." (PMID 32676979, 2021).